EYA2 (EYA transcriptional coactivator and phosphatase 2)
Diseases named in the same sentence as EYA2 in open-access papers (continued):
Sharing a sentence is not in itself a finding about the gene and the disease.
prostate carcinoma (2 papers, 2017 to 2019). A carcinoma that arises from epithelial cells of the prostate gland. "The expression of Eya2 was higher in prostate cancer cell lines compared with the normal RWPE-1 cell line." (PMID 31317026, 2019). "Eya2 protein expression was also higher in prostate cancer cell lines compared with a normal RWPE-1 cell line." (PMID 31317026, 2019). "Collectively, our results highlight the fact that Eya2 is a potential biomarker for prostate cancer." (PMID 31317026, 2019). "The Singh Prostate dataset, provided by Oncomine, suggested that Eya2 was significantly elevated in prostate cancers (n=52) compared with normal prostate gland tissue (n=50) (Mann-Whitney U test, p=0.0158)." (PMID 31317026, 2019). "In the present study, we demonstrated that Eya2 was upregulated in both prostate cancers and cell lines." (PMID 31317026, 2019). "In the present study, we evaluated the expression pattern and biological characteristics of EYA2 in prostate cancer." (PMID 31317026, 2019). "Collectively, these data suggested that Eya2 functions as a promoter for prostate cancer invasion, possibly by regulating MMP7." (PMID 31317026, 2019). "Collectively, these data indicated that Eya2 is upregulated in human prostate cancers and correlates with malignant features." (PMID 31317026, 2019). "Collectively, our current data revealed that EYA2 promoted the progression of prostate cancer, potentially via the AKT/Bcl-2 axis." (PMID 31317026, 2019). "The expression of Eya2 was analyzed in 98 prostate cancer tissues and 16 normal prostate tissues by immunohistochemistry." (PMID 31317026, 2019). "Data from the Cancer Genome Atlas (TCGA) prostate cohort consistently revealed that Eya2 mRNA was positively correlated with a higher Gleason score, higher T stage, and positive nodal metastasis in prostate cancer." (PMID 31317026, 2019). "Matrigel invasion assays further showed that Eya2 promotes the invasion of prostate cancer, which was in accordance with the TCGA data showing positive correlations between Eya2 mRNA and T stage (invading depth) and nodal metastasis." (PMID 31317026, 2019). "However, the clinical significance and biological functions of Eya2 in human prostate cancers remain to be fully elucidated." (PMID 31317026, 2019). "Moreover, Matrigel invasion assays showed that Eya2 transfection increased the invasion ability of prostate cancer cells while shRNA decreased this ability." (PMID 31317026, 2019). "In conclusion, our data demonstrated that Eya2 was upregulated in prostate cancers." (PMID 31317026, 2019). "Furthermore, we explored the potential molecular mechanisms underlying the chemosensitivity and mitochondrial function of EYA2 in prostate cancer cells." (PMID 31317026, 2019). "However, the clinical significance and biological role of Eya2 in human prostate cancer remain unknown." (PMID 31317026, 2019). "Next, we assessed whether Eya2 attenuated the sensitivity of prostate cancer cells to docetaxel." (PMID 31317026, 2019). "Consequently, our data supported the role of the Eya2/AKT/Bcl-2 axis in prostate cancer cells." (PMID 31317026, 2019). "Eya2 protein expression was examined in the normal prostate cell line RWPE-1 and three prostate cancer cell lines (PC-3, LNCaP, and DU145)." (PMID 31317026, 2019). "Furthermore, data from the Oncomine database showed increased levels of EYA2 mRNA expression in prostate cancer tissues compared with normal tissues." (PMID 31317026, 2019).
acute myeloid leukemia (1 paper, 2024). Acute myeloid leukemia (AML) is a group of neoplasms arising from precursor cells committed to the myeloid cell-line differentiation. "One study identified EYA2 as a potential target for molecular therapy in a subtype of acute myeloid leukemia, whereas OCSTAMP mRNA levels were connected to multiple myeloma and TP53RK expression is inversely correlated with multiple myeloma survival." (PMID 38601075, 2024).
allergic disease (1 paper, 2020). An immune response that occurs following re-exposure to an innocuous antigen, and that requires the presence of existing antibodies against that antigen. "The remaining 3 represent novel associations for allergic disease: rs184587444 in SPRR2A, rs4971089 in KRTCAP2, and rs4809619 in EYA2." (PMID 32603359, 2020).
cervical cancer (1 paper, 2021). A primary or metastatic malignant neoplasm involving the cervix. "E2F was upregulated in HPV+ cases, following HPV E7 activation, and EYA2 was also upregulated, which has been shown to promote growth and migration in cervical cancer." (PMID 34944992, 2021).
colorectal neoplasm (1 paper, 2014). A benign or malignant neoplasm that affects the colon or rectum. "On the other hand, enforced expression of Eya2 has been shown to trigger apoptosis in IL-3-dependant myeloid cells, and EYA2 has been found to be aberrantly hypermethylated in most colorectal neoplasms, indicating the potential for EYA2 promoter methylation as a marker of tumorigenesis." (PMID 24810906, 2014).
glioma (1 paper, 2019). A benign or malignant brain and spinal cord tumor that arises from glial cells (astrocytes, oligodendrocytes, ependymal cells). "In gliomas, including GBMs, EYA2 is overexpressed in glioma cells in glioma tissues compared with normal cells and is associated with histological grading." (PMID 30791455, 2019). "EYA2 is overexpressed and regulates growth and invasion of high-grade gliomas including GBMs." (PMID 30791455, 2019).
heart hypertrophy (1 paper, 2016). "Previous studies had revealed that Six1 and its cofactor Eya2 could simulate heart hypertrophy through directly up-regulating mTOR." (PMID 27007909, 2016).
Lewy body dementia (1 paper, 2019). A progressive form of dementia characterized by the presence of protein deposits called Lewy bodies in the midbrain and cerebral cortex, and loss of cholinergic and dopaminergic neurons. "TFDP1 (targeted by miR-30b-5p and miR-365a-3p) is also associated with NFTs in AD, and EYA2 (targeted by miR-219) has been associated with brain pathologies seen in Lewy body dementia." (PMID 31037649, 2019).
non-small cell lung carcinoma (1 paper, 2017). A group of at least three distinct histological types of lung cancer, including non-small cell squamous cell carcinoma, adenocarcinoma, and large cell carcinoma. "Consistently with previous studies, this study showed that EYA2 was up-regulated in both small cell lung cancer and non-small cell lung cancer." (PMID 29340020, 2017).
otosclerosis (1 paper, 2022). Formation of spongy bone in the labyrinth capsule which can progress toward the stapes (stapedial fixation) or anteriorly toward the cochlea leading to conductive, sensorineural, or mixed hearing loss. "In the two other genes, EYA2 and TGFβ1, no variants were found that were significantly associated with otosclerosis after multiple testing correction." (PMID 36498562, 2022).
triple-negative breast carcinoma (1 paper, 2019). An invasive breast carcinoma which is negative for expression of estrogen receptor (ER), progesterone receptor (PR), and human epidermal growth factor receptor 2 (HER2). "IHC analysis displayed that EYA2 protein abundance was inversely associated with the status of ER and PR, and enriched in triple-negative breast cancer in comparison with luminal-type tumors." (PMID 30761270, 2019). "Furthermore, correlation analysis of GSE25066 was performed to explore the association between EYA2 and markers of luminal, triple-negative breast cancer (TNBC), EMT, cancer stem cells (CSCs) as well as the cell cycle-related gene." (PMID 30761270, 2019).
cancer (31 papers, 2010 to 2024). A tumor composed of atypical neoplastic, often pleomorphic cells that invade other tissues. "Our results displayed that EYA2 expression was higher in hormone receptor (HR)-negativebreast cancer tissues in comparison with HR-positive cancerous tissues, while EYA2 mRNA was positively associated with HER2 expression." (PMID 30761270, 2019). "Conversely, we used a specific siRNA to inhibit EYA2 expression in Panc215 cancer cells which yielded a 5.1-fold decrease of EYA2 expression associated with a significant increase in cell proliferation (P=0.0015)." (PMID 24810906, 2014). "High expression of EYA2 issignificantly associated with a shorter overall survival in late stage cancers." (PMID 21423607, 2011). "Additionally, correlation analysis reflected that EYA2 mRNA was negatively correlated with luminal markers, and positively associated with markers of basal cells, epithelial-mesenchymal transition and cancer stem cells." (PMID 30761270, 2019). "Targeting EYA2 tyrosine phosphatase activity in mice with tumors exhibiting a reduced mesenchymal phenotype has been shown to enhance cancer cell immunogenicity, resulting in suppressed tumor growth and improved anti-PD-1 therapeutic response." (PMID 36998461, 2023). "EYA1 stimulated the activity of Cyclin D1, and EYA2 inhibited the transcriptional activity of the ER-β by dephosphorylating the Y36 residue, thus promoting cancer cellular proliferation and tumor growth." (PMID 36750914, 2023). "Downregulation of EYA2 leads to weak mesenchymal phenotypes, increased immunogenicity of cancer cells, reduced carcinogenicity, including tumor growth and metastasis, and increasing infiltration level of natural killer cells (NK cells) and cytotoxic T cells." (PMID 36998461, 2023). "TCGA pan-cancer analysis revealed that the EYA2 expression was significantly increased in cancer, including GBM, LUSC and UCEC, compared with the respective adjacent tissues." (PMID 34044846, 2021). "SIX1 direct interaction with its co-activator EYA2 gives rise to a transcriptional unit that regulates multiple cancer hallmarks, including cell proliferation, invasion, and resistance to apoptosis." (PMID 34771571, 2021). "EYA2 level was lower in cancer samples than normal breast samples while SIX1 level was higher in cancer samples than normal breast samples." (PMID 32550045, 2020). "EYA2 has a notable function in the regulation of cancer biology and serves as a prognostic marker in cancer." (PMID 30791455, 2019). "We found that EYA2 expression was significantly higher in basal-like tumors than luminal-type cancer tissues (p < 0.0001), which was consistent with the results from our meta-analysis." (PMID 30761270, 2019). "The results indicated that protein abundance of EYA2 was significantly higher in ER– (p = 0.005) or PR– (p = 0.004) in comparison with ER+ or PR+ cancer tissues, respectively." (PMID 30761270, 2019). "Over recent years, several studies have reported that Eya2 is involved in the progression of cancer." (PMID 31317026, 2019). "EYA2 promotes cell proliferation and invasion as well as cancer progression by regulating docetaxel sensitivity and mitochondrial membrane potential, possibly via the AKT/Bcl-2 axis." (PMID 31317026, 2019). "Neural lineage markers, such as NCAM1 (early) and NPTX1 (neuronal), were highly expressed in 143BNSC tumours, whereas genes involved in cancer proliferation, including EYA2, VCAN, HMGA1 and TXNIP, were highly expressed in 143BGBM tumours." (PMID 27551510, 2016). "For subsequent experiments, we selected stable clones in which EYA2 expression was comparable to the naturally expressing cancer cell line Panc215." (PMID 24810906, 2014). "Other genes with known roles in cancer included Smoothened, a G-protein coupled receptor in the hedgehog pathway; the transcriptional activator Eya2; the histone-binding oncoprotein SET; and the mTOR inhibitor Depdc6." (PMID 21559491, 2011).
cancer (continued). "The third protein is the EYA2 phosphatase inhibitor, a phosphatase that plays a role in DNA repair and transcriptional regulation, and its inhibitors may have potential as anti-cancer agents, particularly in cases where EYA2 is overexpressed." (PMID 38203761, 2024). "This may be due to the different regulatory mechanisms of EYA2 and the complex tumor heterogeneity on tumor cell proliferation in different cancer cells." (PMID 34044846, 2021). "It should be noted that although EYA2 mutations are rare in HCC and other cancers, they do occur." (PMID 34044846, 2021). "Indeed, the Tyr phosphatase activity of EYA2 was indicated to be critical in the migration of some cancer cell lines." (PMID 32722222, 2020). "A recent study indicated that inhibiting the Tyr phosphatase activity of EYA2 affected lung cancer migration and invasion, suggesting that suppressing the enzymatic activity might be a strategy in cancer therapy." (PMID 32722222, 2020). "It is interesting to speculate that cancer cells might utilize Eya2 to bypass proper genotoxic stress signaling, preventing DDR initiation and thereby promoting rapid cell cycle entry, in addition to its already documented role in cell invasion." (PMID 32142407, 2020). "Recently, the dysregulation of EYA2 has been reported to be involved in several human cancers." (PMID 30761270, 2019). "EYA2 has been implied in tumorigenesis and progression of some cancer types." (PMID 30761270, 2019). "The aberrant expression of Eya2 has been observed in a wide range of cancer types." (PMID 31317026, 2019). "Lastly, the transcription factor EYA2 was shown to be misregulated in a number of cancers." (PMID 30558204, 2018). "Since EYA2-induced migration could be reversed by these compounds, EYA2 phosphatase-specific anti-cancer drugs appear promising." (PMID 27203207, 2016). "Interestingly, Eya2 is also considered a biomarker for certain cancers, indicating that many more types of proliferating cells may up-regulate eya2." (PMID 32142407, 2020). "To begin, we explored the dysregulated transcriptional levels of the EYAs (EYA1, EYA2, EYA3, EYA4) family in 34 types of human common cancer." (PMID 37156847, 2023). "To compare EYA2 protein abundance in ER– vs. ER+ and PR– vs. PR+, we analyzed a TMA containing 125 informative cancer tissue points by IHC." (PMID 30761270, 2019). "Further investigation on EYA2’s mode of action and the possible involvement of Jak/STAT signaling in cancer metastasis are interesting areas yet to be understood." (PMID 30558204, 2018). "Thus, miR-338-3p activation may be useful for treatment of cancer with EYA2 overexpression." (PMID 28703807, 2017). "Moreover, FBXW7 can ubiquitinate and degrade Eyes absent homolog 2 (EYA2), leading to increased immunogenicity of cancer cells, reduced carcinogenicity, and increased infiltration of natural killer (NK) cells and cytotoxic T cells." (PMID 39748950, 2024). "Elucidating the roles of EYA2, acting as tumor suppressor will shed light on the molecular basis of HCC and may suggest therapeutic strategies for the malignant tumors." (PMID 34044846, 2021). "EYA proteins facilitate tumor progression and are independent prognostic factors in breast and ovarian cancer, but not in pancreatic cancer, in which epigenetic silencing of EYA2 increases the cancer invasion capacity." (PMID 27203207, 2016). "We found the EYA2 CpG island unmethylated in HPDE and the EYA2-expressing cancer cell line, Panc215, but it was methylated at most or all CpGs sequenced in the non-expressing Panc2.8 and A38-5 cell lines, respectively, and remained unmethylated in the non-expressing Panc2.5 and Panc3.014 cells." (PMID 24810906, 2014). "Eyes absent 2 (EYA2) is upregulated inovarian cancer compared to normal ovarian surface epithelium in part due to genomicamplification." (PMID 21423607, 2011).
tumor (17 papers, 2014 to 2025). "We report that Eyes absent homolog 2 (EYA2) suppresses the HCC progression, while EYA2(A510E) mutation identified by exome sequencing attenuates the tumor-inhibiting effect of EYA2." (PMID 34044846, 2021). "The present work is the first reporting the role of EYA2 in suppressing the malignant phenotype of HCC, and the somatic mutation p.A510E of EYA2 that neutralized the tumor inhibitory effect of EYA2." (PMID 34044846, 2021). "In contrast, EYA2 overexpression significantly reduced the subcutaneously tumorigenic ability of the tumor cells in nude mice, and EYA2(A510E) mutation dispelled the inhibitory effect." (PMID 34044846, 2021). "Likewise, another signaling axis, EGFR/miR-338-3p/EYA2, has been linked by a recent study to tumor growth and lung metastasis." (PMID 34206026, 2021). "Several mechanisms might underlie the role of EYA2 in tumor invasion, including the activation of ERK signaling and the promotion of epithelial-mesenchymal transition (EMT)." (PMID 30761270, 2019). "Functionally, EYA2 acts as a transcriptional coactivator and has been shown to promote tumor growth in xenograft models." (PMID 40422184, 2025). "By contrast, the expression of EYA2 was higher in the immune cells and tumor areas of the recur group." (PMID 40422184, 2025). "MiR-338-3p inhibited EGFR and subsequently activated EYA2, which accelerates BC tumor cell growth and lung metastasis." (PMID 36750914, 2023). "In human MDA-MB-231 tumor-bearing mice, treatment of the mice with an EYA2 inhibitor, namely MLS000544460, demonstrated anti-tumor effects." (PMID 35572601, 2022). "The 2 × 107 TU lentivirus carrying the EYA2 gene that was injected into the tail vein of nude mice had a good inhibitory effect on the tumor growth in situ." (PMID 34044846, 2021). "Taken together, these data demonstrate that EYA2 acts as a tumor suppressor to prevent the initiation and progression of HCC, while EYA2(A510E) mutant type attenuates the inhibitory function." (PMID 34044846, 2021). "Of note, evidences obtained from both in vivo and in vitro experiments pointed towards EYA2 functions as a tumor suppressor in HCC." (PMID 34044846, 2021). "The tumor-suppressing role of EYA2 in HCC is unexpected because the previous experiments indicated a positive role of EYA2 in regulation of pro-metastatic characteristics of breast cells through the TGF-β pathway by working in concert with SIX1 protein." (PMID 34044846, 2021). "In an attempt to assess the function of EYA2 on multiple cancer cells, we found that overexpression of EYA2 had a weak ability to affect tumor cell proliferation in HT-29, PANC-1 and MCF-7 cell lines, but sturdy in MHCC-97H, Huh-7 and A549 cell lines." (PMID 34044846, 2021). "The tumor volume (P = 0.0398) and tumor weight (P = 0.0368) in the 2 × 107 TU lentivirus-EYA2 group were significantly reduced compared with those in the control group." (PMID 34044846, 2021). "Multivariate analysis revealed that the serum α-fetoprotein (P = 0.030), tumor differentiation (P = 0.040) and EYA2 protein expression (P = 0.042) were independent prognostic factors for the overall survival." (PMID 34044846, 2021). "A recent study has demonstrated that microRNA-338-3p/EYA2 axis led to epidermal growth factor receptor (EGFR)-induced tumor growth and lung metastasis." (PMID 30761270, 2019). "Meta-analysis showed that EYA2 mRNA expression was correlated with tumor grade, the status of estrogen receptor (ER), progesterone receptor (PR), and human epidermal growth factor receptor 2 (HER2)." (PMID 30761270, 2019). "Here we found that EYA2 expression is significantly higher in tumor tissue compare to those in paired adjacent non-tumor tissues." (PMID 29340020, 2017). "The results showed that expression of EYA2 was significantly higher in tumor tissues than in adjacent non-tumor tissues (*p < 0.05)." (PMID 29340020, 2017).